MSTN (myostatin)
Diseases named in the same sentence as MSTN in open-access papers (continued):
Sharing a sentence is not in itself a finding about the gene and the disease.
Cachexia (continued). "Further studies with this model may shed light on its potential application to the treatment of muscle dystrophy and cachexia by depressing myostatin activity." (PMID 19586544, 2009). "Therefore, we suggest that curcumin may reduce the expression of muscle degrading factor myostatin and increase the myogenic factor myogenin to achieve the effect of reducing cachexia-related muscle atrophy." (PMID 35132306, 2022). "Similarly, the association between myostatin circulating levels and cachexia is not completely clear." (PMID 36078078, 2022). "Many cachexia-inducing factors such as activin A (ActA), myostatin (Mstn), and growth/differentiation factor 15 (GDF15) are members of the transforming growth factor (TGF)-β family, capable of inducing muscle wasting and fat loss in preclinical cancer cachexia models." (PMID 33925872, 2021). "We found 71 proteins that correlated with cachexia severity via weight loss grade, weight loss, skeletal muscle index and radiodensity (r ≥ |0.50|, p ≤ 0.05), including some known cachexia mediators/markers (LEP, MSTN, ALB) as well as novel proteins (e.g., LYVE1, C7, F2)." (PMID 33334063, 2020). "Together with data demonstrating that blockade of the myostatin/ActRIIB pathway is highly beneficial in models of cancer-induced cachexia, our results indicate that ActRII blockade might be beneficial in cachectic cancer patients which are or have been exposed to chemotherapies." (PMID 27462398, 2016). "Furthermore, the UPS and myostatin/activin signaling pathways may play important roles in radiation-induced cachexia." (PMID 27029502, 2016). "With the TGF-β superfamily, proteins, such as activins A and B, as well as myostatin (MSTN), have been investigated the most in the context of cachexia." (PMID 38334644, 2024). "Myostatin and activin signaling, IGF-1/PI3K/AKT signaling, and JAK-STAT signaling are known to play roles in cachexia, and thus, these pathways are considered potential therapeutic targets." (PMID 35565236, 2022). "However, future studies are needed to validate the results of the present study, and prospective longitudinal studies should be performed to identify whether the baseline myostatin level could be utilized to predict differences in relevant outcomes of patients with regard to cachexia and myopenia." (PMID 35592686, 2022). "In multiple mouse models with cachexia, an ACVR2B antibody blocking both myostatin and activin activity reduced muscle wasting." (PMID 36078078, 2022). "Our results demonstrated that the protein levels of atrogin-1, MuRF-1, myostatin, and p-STAT3 were higher in the cachexia group than in the NC group." (PMID 36230949, 2022). "In relevance to cachexia, our recent study shows that SIRT6 was able to downregulate expression of myostatin (MSTN), a member of the transforming growth factor (TGF)‐β family and a known potent negative regulator of skeletal muscle mass." (PMID 34212132, 2021). "As myostatin and activins have been implicated in the pathogenesis of cancer cachexia, we next sought to determine if TMEPAI could prevent loss of muscle mass in a mouse model of cancer cachexia, induced by the subcutaneous growth of an implanted colon-26 (C26) carcinoma in male BALB/c mice." (PMID 33250771, 2020). "More specifically, TGF-β is a potent inducer of muscle atrophy through activin, inhibin, and myostatin, all part of the TGF-β protein family, which are shown to have a significant role in cachexia." (PMID 26172047, 2015). "Increased levels of myostatin in patients with heart failure-driven muscle unloading or cancer-related cachexia seem to confirm its role as a negative skeletal muscle regulator." (PMID 39683624, 2024). "Myostatin plays a relevant role in the development of muscle atrophy by inducing cachexia in nonrheumatic patients and experimental studies." (PMID 35592686, 2022).
Cachexia (continued). "MSTN induced cachexia has been reported to be triggered by the activation of the ubiquitin-proteasome system (UPS) via FOXO1-dependent signaling, and it has been shown that increased MSTN expression is involved in the production of COPD-related muscle atrophy." (PMID 35812316, 2022). "The expression of atrogin-1, MuRF-1, myostatin, and p-STAT3 was significantly reduced by the 2-DG treatment and prevented the transcriptional activation of MuRF-1 and atrogin-1, which was markedly increased in the cachexia group." (PMID 36230949, 2022). "Similarly, myostatin (growth and differentiation factor 8; GDF-8), belonging to the transforming growth factor-β (TGF-β) superfamily, seems to play a critical role in cachexia being a negative regulator of muscle growth." (PMID 34445710, 2021). "Cardiac-specific deletion of myostatin (a transforming growth factor β [TGF-β] family member) reduced muscle atrophy, and myostatin-targeting therapies have been proposed for treatment of cachexia and muscular dystrophy." (PMID 34479416, 2021). "Moreover, the ability of PAR2 to control ALK5 protein abundance suggests the possibility that PAR2 can enhance the cellular actions of other TGF-β superfamily members, such as myostatin and GDF15, eventually leading to cancer-cachexia and muscle wasting." (PMID 27916875, 2016). "Similar results were found upon treatment of cachectic rodents with anti-myostatin inhibitors, where signs of cachexia were reversed without affecting IL-6 or TNF-α plasma levels." (PMID 25460504, 2015). "Myostatin negatively regulates skeletal muscle mass, though inhibition of its downstream pathways does not attenuate C26-induced cachexia, thereby suggesting that myostatin does not play a role in this context." (PMID 20615237, 2010). "Its dual role in stimulating AKT/mTOR signaling and modulating myostatin-SMAD pathways highlights its potential as a candidate for combination therapy, potentially engaging novel feedback loops and receptor crosstalk mechanisms relevant to muscle regeneration and anti-cachexia strategies." (PMID 41302540, 2025). "Based on our previous literature review, cachexia is a complex syndrome connected with several signaling pathways, including TGF-β signaling activation, PI3K/Akt/mTOR signaling, the renin–angiotensin–aldosterone system (RAAS) pathway, myostatin and activin signaling, and the hypoxia/HIF-1 pathway." (PMID 38203330, 2023). "Moreover, several myostatin modulators have already reached clinical trial phase for a broad range of indications, including muscular dystrophy, sporadic inclusion body myositis (IBM), cachexia, aging-related muscle atrophy, obesity, type 2 diabetes, and SMA." (PMID 35727341, 2022). "Inhibition of myostatin- and activin-mediated SMAD2/3 signaling using ligand traps, such as soluble receptors, ligand-targeting propeptides and antibodies, or follistatin can increase skeletal muscle mass in healthy mice and ameliorate wasting in models of cancer cachexia and muscular dystrophy." (PMID 33250771, 2020). "Finally, we found drugs targeting MSTN, CXCL12, and CAMK2B, which may be considered for the development of novel therapeutic strategies for cancer-related cachexia." (PMID 31013615, 2019). "Considering that Myostatin was shown to play a pivotal role in muscle wasting in other diseases and the fact that cachexia is a negative prognostic factor in critical illness we hypothesized that Myostatin might play a relevant role in the course of critically ill patients with and without sepsis." (PMID 32784522, 2020). "Additionally, any proposed treatment for cachexia, such as reducing the activity of catabolic mediators (ie. cytokines, myostatin) that activate proteolysis and lipolysis, without addressing the energetic burden of the cancer will potentially have limited impact." (PMID 26370269, 2015).
Insulin resistance (95 papers, 2009 to 2026). Increased resistance towards insulin, that is, diminished effectiveness of insulin in reducing blood glucose levels. "Transgenic mouse models with overexpression of MSTN propeptide also resist increases in adipose tissue mass and insulin resistance, which are associated with a high-fat diet, while wild-type counterparts develop prediabetes." (PMID 39340593, 2025). "Compensatory hyperinsulinemia caused by insulin resistance leads to inadequate inhibition of glycogen generation, accelerated protein degradation, reduced protein synthesis, and increased myostatin content, ultimately resulting in skeletal muscle loss." (PMID 39803274, 2025). "Higher serum myostatin levels were associated with lower insulin sensitivity by Matsuda index and higher insulin resistance by HOMA‐IR, which remained significant after controlling for sex (p = 0.04 and p = 0.03, respectively)." (PMID 39261976, 2024). "Following observations of resistance to high-fat diet-induced impairment of glucose tolerance in myostatin-knockout mice, it was reported in humans that greater myostatin expression was associated with insulin resistance." (PMID 37801203, 2024). "Increased MSTN concentrations predispose to the development of metabolic disorders such as insulin resistance." (PMID 39124846, 2024). "The pathophysiological mechanisms that link the two entities of the disease are insulin resistance, inflammation, nutritional deficiencies, impairment of myostatin and adiponectin, or physical inactivity." (PMID 38255652, 2023). "Animal studies have demonstrated that deficiency in myostatin promotes muscle growth and protects against insulin resistance." (PMID 36875483, 2023). "In humans, elevated myostatin levels in skeletal muscle or circulation have been associated with obesity and insulin resistance in adults." (PMID 36875483, 2023). "A previous study reported that the factors associated with muscle atrophy in T2DM are increased myostatin, endogenous glucocorticoids, and insulin resistance." (PMID 30332436, 2018). "A loss-of-function mutation in either one or both alleles of the myostatin gene was able to protect mice against obesity-induced insulin resistance." (PMID 24454989, 2013). "In the present study a positive association was also observed regarding muscle myostatin mRNA and both BMI and insulin resistance as measured by HOMA in normal controls subject." (PMID 22615949, 2012). "Indeed, insulin resistance has previously been associated with increased mRNA expression and serum abundance of myostatin in humans." (PMID 37801203, 2024). "Hyperinsulinemia associated with insulin resistance elevates serum myostatin levels." (PMID 39685530, 2024). "Decreased insulin resistance in myostatin deficient rats was attributed to a significant activation of the AMPK signaling pathway and increased adiponectin, an insulin sensitizing adipocytokine, secretion which enhances the oxidation of fatty acids in skeletal muscles." (PMID 37576807, 2023). "Additionally, increased myostatin in muscle has also been reported in metabolic conditions associated with insulin resistance such as type 2 diabetes and dysglycemia." (PMID 35287731, 2022). "Elevated MSTN levels are also associated with increased insulin resistance." (PMID 35011721, 2022). "The association of myostatin plasma levels and insulin resistance was contrary to our hypothesis with decreased values in patient with more severe insulin resistance." (PMID 35922829, 2022). "The compensatory downregulation could also extend beyond muscle atrophy into insulin signaling as insulin resistance is a common observation during critical illness and high myostatin levels have also been associated with insulin resistance." (PMID 35922829, 2022). "Insulin resistance of the skeletal muscle is associated with reduced activity of Akt kinase, and low Akt activity leads to the activation of FoxO1, which increases the MSTN mRNA levels in C2C12 myotubes." (PMID 32316589, 2020).
Insulin resistance (continued). "In humans, however, results of several studies were inconsistent with each other; the serum MSTN level was significantly reduced in individuals with the metabolic syndrome, while insulin resistance and BMI were associated with MSTN expression in the skeletal muscle in ex-obese subjects." (PMID 26502079, 2015). "Increased myostatin mRNA expression might be a predisposing marker for the development of insulin resistance in healthy subjects." (PMID 22615949, 2012). "Furthermore these human data reveal a positive association between insulin resistance and myostatin mRNA expression in the skeletal muscle in healthy subjects." (PMID 22615949, 2012). "While MSTN expression increases with age, a recent study found that MSTN mRNA is uniquely elevated in older people with excess adiposity and insulin resistance." (PMID 41011274, 2025). "APS can reduce hyperglycemia, insulin resistance, and inhibit myostatin secretion from skeletal muscle, thereby inhibiting bone muscle loss." (PMID 41154559, 2025). "For example, maternal Omega-3 PUFA intake during pregnancy affects offspring DNA methylation, influencing genes like MSTN, IFNA13, ATP8B3, and GABBR2, which are linked to insulin resistance, adiposity, and immune responses." (PMID 40507105, 2025). "Some organokines have protective effects (e.g., FGF-21, irisin, and klotho), while others, such as myostatin and fetuin-A, exacerbate insulin resistance and fibrosis." (PMID 41373697, 2025). "There are data that confirm the impact of conditions such as insulin resistance, chronic inflammation, cirrhosis, or arteriosclerosis on the increased production of MSTN antagonists such as irisin, follistatin, or IGF-1." (PMID 38542721, 2024). "Future prospective, longitudinal studies should investigate myostatin as a biomarker or potential therapeutic target for insulin resistance." (PMID 39261976, 2024). "Concordantly, myostatin protein and plasma abundance were shown to be reduced in middle-aged insulin-resistant men, following long-term aerobic exercise, despite an absence of weight loss or a reduction in fat mass." (PMID 37801203, 2024). "Women had lower mean weight, ALM, ALM/weight, VAT, and serum myostatin levels (p < 0.05), and similar mean insulin sensitivity by Matsuda index and insulin resistance by HOMA‐IR, than men." (PMID 39261976, 2024). "The present study found that mice with brown adipocyte–specific deletion of MSTN exhibited diet-induced insulin resistance, glucose intolerance, and hepatosteatosis, contrary to the phenotypes of MSTN global-KO mice." (PMID 38889010, 2024). "In a multivariate model including myostatin, BMI, VAT, ALM, and sex, myostatin remained significantly negatively associated with insulin sensitivity by Matsuda index (p = 0.04) and insulin resistance by HOMA‐IR (p = 0.04)." (PMID 39261976, 2024). "The concentration of MSTN is closely related to the occurrence and development of diabetes or insulin resistance." (PMID 37288303, 2023). "In line with this, studies exploring myostatin in humans state a positive correlation between myostatin and insulin resistance." (PMID 35631274, 2022). "While it is well-established that a primary action of myostatin is to inhibit muscle growth, new evidence suggests it can also play a key role contributing to metabolic dysfunction and insulin resistance." (PMID 35287731, 2022). "Myostatin has also been shown to play a role in insulin resistance as it inversely correlates with insulin sensitivity in healthy adults." (PMID 35922829, 2022). "Consistent with a role in adipose tissue, myostatin knockout mice had shown a reduced fat pad mass and were resistant to obesity and insulin resistance." (PMID 35563026, 2022). "Insulin resistance promotes glycogenesis, accelerates protein degradation, reduces protein synthesis and induces myostatin which lead to the decline of skeletal muscle." (PMID 36438727, 2022).
Insulin resistance (continued). "Circulating myostatin is basically increased in obese subjects; its concentration correlates positively with insulin resistance/pancreatic β-cell dysfunction indicators and negatively with insulin sensitivity indicators." (PMID 34959945, 2021). "In fact, in patients with sarcopenic obesity, an elevated myostatin level is correlated with insulin resistance." (PMID 34680417, 2021). "In mice models, the pharmacological blockade of myostatin induces muscle mass gain and improves metabolic management of insulin, triglycerides, and circulating adiponectin in obese mice with insulin resistance." (PMID 34680417, 2021). "Myostatin’s impact extends beyond muscles, with alterations in myostatin present in the pathophysiology of myocardial infarctions, inflammation, insulin resistance, diabetes, aging, cancer cachexia, and musculoskeletal disease." (PMID 33854530, 2021). "Extremely obese women secrete and express increased amounts of myostatin in skeletal muscle, which correlate with insulin resistance." (PMID 34641817, 2021). "Myostatin has also been suggested to be a promoter of insulin resistance, and aerobic exercise has the effect of suppressing circulating levels of myostatin." (PMID 31555646, 2019). "Inhibition of myostatin activity by myostatin propeptide significantly attenuated insulin resistance in mice fed with a high-fat diet." (PMID 28432282, 2017). "We showed that APS treatment ameliorated hyperglycemia, hyperlipidemia, and insulin resistance, which were associated with the decreased MDA and myostatin level in the skeletal muscle of KKAy mice." (PMID 24454989, 2013). "Recent studies suggest that myostatin plays a major role in regulating insulin signaling and insulin resistance." (PMID 24454989, 2013). "Recent studies suggest that skeletal muscle secreted growth factor myostatin plays an important role in regulating insulin signaling and insulin resistance." (PMID 24454989, 2013). "This palmitate-induced insulin resistance coincided with a 3.3-fold increase in myostatin accumulation." (PMID 24454989, 2013). "Altered MSTN and adipokine secretion may contribute to several clinical complications observed in individuals with PWS, including insulin resistance/diabetes, and is implicated in visceral fat accumulation, low muscle mass, and muscle weakness." (PMID 41303309, 2025). "This study sought to delineate between the effects of excess adiposity, insulin resistance and ageing on myostatin mRNA expression in human skeletal muscle and to undertake in vitro investigations using human primary muscle cultures to explore possible causative factors." (PMID 37801203, 2024). "In T2D, insulin resistance prevents muscle growth (accelerator function); thus, myostatin (i.e., the brake for muscle growth) might reduce as there is no need for a brake as there is not an increased accelerator function." (PMID 39590324, 2024). "Skeletal muscle produces myokines, including myostatin, that may play a mechanistic role in the development of insulin resistance." (PMID 39261976, 2024). "Taken together, these findings suggest that whilst the upregulation of myostatin may exacerbate insulin resistance in individuals with excess adiposity, lipid-induced insulin resistance does not induce its upregulation." (PMID 37801203, 2024). "Upon exercise, myostatin decreases, and its expression has been correlated to a decrease in plasma levels of glucose, insulin, and IL-6 and a reduction in IR (calculated with the Homeostatic Model Assessment for Insulin Resistance Index, HOMA-IR)." (PMID 39337980, 2024). "In transgenic rats with the suppressed function of myostatin, insulin signaling was significantly activated and high-fat diet failed to cause glucose intolerance or insulin resistance as compared to wild-type rats." (PMID 37576807, 2023).